XBP1 (X-box binding protein 1)
Diseases named in the same sentence as XBP1 in open-access papers (continued):
Sharing a sentence is not in itself a finding about the gene and the disease.
inflammatory bowel disease (28 papers, 2009 to 2025). A spectrum of small and large bowel inflammatory diseases of unknown etiology. "For example, the transcription factor XBP1 was identified as a risk factor for human inflammatory bowel disease." (PMID 34530836, 2021). "Hereditary polymorphisms in the gene encoding XBP1 have been associated with inflammatory bowel disease (IBD), a condition that is believed to arise from dysregulation in host immune responses to enteric microflora." (PMID 23724040, 2013). "Unlike the other genes discussed in this section, the functional association of X box-binding protein 1 (Xbp1) with intestinal inflammation came first and inspired analysis of its genetic linkage to inflammatory bowel disease." (PMID 21994779, 2011). "Both, Atg16l1 and Xbp1 are known risk genes for inflammatory bowel disease (IBD)." (PMID 41057521, 2025). "Furthermore, multiple single nucleotide polymorphisms of X-box binding protein 1 (XBP1) were found to be associated with inflammatory bowel disease in independent whole genome analysis studies." (PMID 24194940, 2013). "Based on these results in mice, the authors questioned whether human XBP1 is mutated in inflammatory bowel disease patients." (PMID 21994779, 2011). "Arthur and colleagues found that aberrant expression of XBP1 in intestinal epithelial cells induces endoplasmic reticulum stress, which leads to intestinal inflammation, suggesting that XBP1 expression is strongly associated with developing inflammatory bowel disease." (PMID 39987439, 2025). "ER stress and SNPs in the XBP1 locus have also been linked with the risk of inflammatory bowel disease (IBD) development in humans." (PMID 38949019, 2024). "Discovery of several single-nucleotide polymorphisms on XBP-1 gene related to inflammatory bowel disease (IBD) has pointed out a link between ER stress and tissue specific inflammatory pathologies." (PMID 25216759, 2014). "Deletion of XBP1 in intestinal epithelial cells induces inflammation and develops inflammatory bowel disease (IBD)." (PMID 34072430, 2021). "Further, we found known associations between KLF6, NR3C1, XBP1 and HSF1 with inflammatory bowel disease further validating our analyses." (PMID 30184180, 2018). "XBP1 also correlates with human inflammatory bowel disease (IBD) and Crohn’s disease." (PMID 29323257, 2018). "Thus, our results highlight the importance of the ISR in the immune response of the intestinal epithelium, which is in agreement with reports linking stress signaling, such as XBP1-dependent pathways, with inflammatory bowel disease." (PMID 27561422, 2016). "Several IEC signature TFs have known associations with human Inflammatory Bowel Diseases (IBD), including SMAD7, CEBPG, STAT3, XBP1, HNF4A, ELF3, IRF1, and NFκB components IKBKB, IKBKG, and NFKBIZ." (PMID 28850571, 2017). "In the colon and small intestine of patients with inflammatory bowel disease, ER stress and the UPR go hand in hand with increased GRP78 expression and spliced X-box binding protein 1 (XBP1s) mRNA." (PMID 24194940, 2013). "Intestinal inflammation in inflammatory bowel disease (IBD) emerges from dysfunction in these cells due to excessive ER stress, which may be an after effect of broad range of factors like primary genetic (abnormalities in UPR, XBP1) and secondary (inflammation, environmental)." (PMID 25120434, 2014).
viral infection (27 papers, 2007 to 2025). "While in both the wild-type and Ube2g2-deficient cells, virus infection triggered increased Xbp1 splicing, the basal levels of spliced Xbp1 were substantially higher in Ube2g2−/− cells compared to that of wild-type." (PMID 37164963, 2023). "This VACV infection-associated decrease in XBP1 mRNA splicing is so remarkable that virus infection is able to counteract the tunicamycin-induced XBP1 splicing, considering that the drug is a potent inducer of UPR activation and IRE1α activation." (PMID 37434252, 2023). "In NK cells, IRE1α-XBP1 signaling during viral infection drives oxidative phosphorylation mediated by c-Myc, while XBP1s inhibits mitochondrial function in tumor-infiltrating T cells." (PMID 36475773, 2023). "Prior report showed a critical role of the ER stress sensor IRE1α and its substrate transcription factor XBP1 in promoting NK cell effector responses to fend off virus infection and to clear tumors." (PMID 36361628, 2022). "In conclusion, XBP1 has a dual role in response to viral infection, that is, promoting viral replication and playing an antiviral role." (PMID 35269888, 2022). "Dengue virus infection activates the IRE1α/XBP1 pathway, thereby triggering ER stress-mediated apoptosis and alleviating the cytotoxicity of viral infection." (PMID 35269888, 2022). "The virus titer increased with the increase of ROS; hence, XBP1-s finally exacerbated the viral infection." (PMID 35269888, 2022). "Viral infection induced expression of the ER-resident chaperone hsp-4 (BiP orthologue) and triggered splicing of xbp-1." (PMID 36471127, 2022). "In relation to ERAD, this IRE1α-XBP1-mediated pathway counters viral infections by degrading unfolded viral proteins, thereby limiting viral replication." (PMID 34122136, 2021). "WP1130-induced unfolded protein response (UPR) blocks specific viral infection via activating the X-box binding protein-1 (XBP-1) in murine macrophages, suggesting its potential use for broad spectrum antiviral therapies." (PMID 26097878, 2015). "Each flavivirus has its own signature for activating the IRE1/XBP1-signaling pathways with unique benefits to virus infection." (PMID 24653727, 2014). "In the future, it will be important to determine whether the divergent patterns of IREα-XBP1 signaling in response to viral infection observed here will be generalizable to diverse cell types and model systems." (PMID 40005508, 2025). "We discuss how these apparently paradoxical effects on the IRE1α-XBP1 signaling axis might coordinately optimize viral replication during the rapid changes in the intracellular environment that accompany viral infection." (PMID 40005508, 2025). "Additionally, our findings showed that viral infection activated the ER stress pathway IRE1α/XBP1, which upregulated SCD1 expression and promoted the synthesis of triglycerides (TG) and lipid droplets (LDs)." (PMID 40387378, 2025). "Furthermore, the IRE1α-XBP1 axis promotes fibronectin-rich matrix deposition during viral infection, and calreticulin-mediated ER stress facilitates TGF-β signaling and ECM assembly in fibrotic tissues." (PMID 40501821, 2025). "XBP1-s is produced upon exposure to endoplasmic reticulum (ER) stress resulting from changes in extrinsic and intrinsic factors, including microenvironment, overproduction of reactive oxygen species (ROS), excessive proliferation, and viral infection." (PMID 35269888, 2022). "We then tested whether MPCMK, a viral 2A protease inhibitor, abrogates the observed effects of the viral infection on the stress-induced Xbp1 mRNA splicing." (PMID 36366584, 2022).
viral infection (continued). "The results showed that the XBP1s mRNA level and the XBP1 splicing degree were constant during viral infection, but increased in Tg-treated cells, which is consistent with previous reports, and confirms that IRE1α RNase activity was not activated by HSV-1 infection." (PMID 28832521, 2017). "Xbp-1 mRNA splicing constitutes a marker of the induction of the unfolded protein response, a finding that has been related to autophagic process during the viral infection." (PMID 24205422, 2013). "In addition, virus infection of monocytic cells can activate XBP1 splicing and Grp78 (Bip) expression." (PMID 23724040, 2013). "Furthermore, it is known that XBP-1 activation/overexpression is a downstream target of the ER stress response pathway, which is perturbed in the setting of viral infections and inflammatory responses." (PMID 17418411, 2007). "Thus, viral infection may be sufficient to trigger XBP1 splicing, but limit broader RNA degradation." (PMID 37306512, 2023). "In the early stages of viral infection, flaviviruses trigger the IRE1/XBP1 arm of the UPR to reduce the cytotoxicity of viral infection." (PMID 41386297, 2025). "The UPR marker XBP1 is essential for surface presentation of MHC I in DCs and activation of CD8+ T cell response to virus infection (32, –34)." (PMID 35149556, 2022). "IRE1α-XBP1 is also activated in CD8+ T cells, in response to bacterial and viral infections and the pathway plays an important role in terminal effector functions." (PMID 34122136, 2021). "To gain better insight about the process affected by XBP-1, we induced the deletion of XBP-1 immediately after the entry phase, in the course of viral infection." (PMID 25333725, 2014). "Viral infection did not result in the accumulation of spliced XBP1 mRNA." (PMID 40143290, 2025). "Furthermore, XBP1-s can aggravate inflammation by binding directly to the promoters of inflammatory factors such as interleukin-8 (IL-8), chemokine ligand 5 (CCL5), and interferon β (IFN-β), and can exacerbate viral infection by promoting viral DNA replication." (PMID 35269888, 2022). "The results showed that EDEM1 gene, calreticulin, and calnexin mRNA levels were all not modified in cp BVDV-infected MDBK cells, indicating that viral infection did not activate the ATF6 and XBP1 signaling pathways." (PMID 36939351, 2023). "The IRE1α/XBP1 pathway is one of the UPR signaling networks commonly activated by ER stress or by other physiological stimuli not limiting to lipid perturbation, immune response or viral infection." (PMID 36768338, 2023).
colorectal cancer (26 papers, 2016 to 2025). A primary or metastatic malignant neoplasm that affects the colon or rectum. "We aim to identify the expression and analyze the molecular action of dysregulated lncRNA-miRNA mediated by XBP-1 in colorectal cancer (CRC)." (PMID 34521445, 2021). "The interreaction between UPR pathways: serving as UPR effector proteins, ATF6 and XBP1, mitigate colorectal cancer cell proliferation and stemness by activating PERK signaling." (PMID 33514437, 2021). "A recent study showed that activation of the IRE1α-XBP1 pathway promoted cell proliferation and invasion by playing a major role in epithelial to mesenchymal transition in colorectal cancer." (PMID 32034256, 2020). "K114 inhibited ER stress-induced splicing of XBP1 mRNA as well as reporter luciferase expression in HCT116 cells derived from human colorectal carcinoma, and inhibited ribonuclease activity of human IRE1α in vitro." (PMID 31875595, 2020). "To exclude a cell line specific effect of the observed growth disadvantage upon expression of XBP1(s) or ATF61–373, we generated two alternative colorectal cancer cell lines harboring inducible expression of XBP1(s) and ATF61–373 (SW480 and DLD-1, Supp." (PMID 31227689, 2019). "We generated colorectal cancer cells (LS174T) that harbor doxycycline inducible expression of the active forms of either XBP1(s) or ATF61-373." (PMID 31227689, 2019). "Similar findings have also been reported in colorectal carcinoma (CRC) where the IRE1α-XBP1 pathway promotes proliferation and invasion of CRC cells." (PMID 27536557, 2016). "Moreover, tumor-associated macrophages (TAMs), a predominant myeloid cell population in numerous cancers, exhibit increased XBP1 splicing in TAMs isolated from colorectal cancer patients compared to peripheral monocytes or macrophages." (PMID 39080273, 2024). "Activation of XBP1 in TAMs promotes the progression of colorectal cancer, which may be related to the upregulation of SIRPα and THBS1, and the inhibition of macrophage phagocytosis." (PMID 37954130, 2023). "Also, the expression of XBP1 was correlated with EGFR in colorectal cancer patients database GSE 38822." (PMID 32489465, 2020). "However, HSPA5 positively correlated with spliced XBP1 mRNA in the colorectal cancer tissues." (PMID 27034162, 2016). "The inhibitor proved to be effective against ER stress-induced XBP1 mRNA splicing in human colorectal cancer HCT116 cells, and it was shown to inhibit the cleavage of XBP1 mRNA by purified IRE1-C in vitro as effectively as 4μ8C, in a dose-dependent manner." (PMID 33562589, 2021). "To validate these results, we further examined the ER-stress-related proteins, including BiP, Ero1-Lα, PERK, eIF2α, p-eIF2α, IRE1α, XBP-1 s, and CHOP in colorectal cancer cells treated with different concentrations of DEH for 48 h." (PMID 33838688, 2021). "For example, activity of XBP1-s leads to promote CRC cell proliferation by inhibiting TAp73 transcriptional activity; but Xbp1 reduces colorectal cancer cell proliferation and stemness by activating PERK signaling in CRC cell LS174T." (PMID 33997035, 2021). "To investigate the relationship between FOXM1 with ER stress in colorectal cancer, we first analyzed HSPA5, spliced XBP1 and FOXM1 mRNA expression by qRT-PCR in colorectal cancer specimens." (PMID 27034162, 2016). "To exclude the possibility of transcriptional upregulation of both HSPA5 and FOXM1 induced by hypoxia in advanced colorectal cancer, we analyzed the correlation between FOXM1 and spliced XBP1 mRNA, an indicator of ER stress." (PMID 27034162, 2016). "Plasmid to express the respective XBP1 protein was transfected into the human colorectal carcinoma cell line HCT116 together with or without plasmid to express medaka IRE1α, and their cell lysates were analyzed by Immunoblotting." (PMID 28952924, 2017).
colorectal cancer (continued). "Additionally, we found statistically significant positive correlations between spliced XBP1 and HSPA5 mRNA expression in colorectal cancer (r = 0.443, P = 3.12×10−6)." (PMID 27034162, 2016). "In this study, to investigate whether endoplastic reticulum (ER) stress correlated with FOXM1 in colorectal cancer, we analysed the mRNA levels of FOXM1 and ER stress markers HSPA5 and spliced XBP1 by qRT-PCR." (PMID 27034162, 2016). "Not only was XBP1 found to be elevated in response to Klotho, exposure to a UPR inhibitor, tauroursedeoxycholic acid (TUDCA), partially rescued the effect of Klotho on colorectal cancer cell colony formation, supporting the ability of Klotho to modulate UPR pathways." (PMID 32585905, 2020). "Moreover, analysis of TCGA colorectal cancer data using the GEPIA2 online tool revealed that STK26 exhibits significant positive correlations with mRNA expression levels of ATF6 pathway downstream effectors (HSPA5, XBP1), clinically corroborating our experimental findings." (PMID 40869379, 2025).
prostate carcinoma (24 papers, 2007 to 2025). A carcinoma that arises from epithelial cells of the prostate gland. "IT-139 at 500 μM caused large increase in XBP-1 mRNA splicing in Tg-stressed C4-2B and LNCaP prostate cancer cell lines, consistent with GRP78 depletion." (PMID 30038714, 2018). "IRE1a-X-Box Binding Protein 1 (XBP1) pathway has also been proven by activating c-MYC signaling pathway to support the growth of prostate cancer cells." (PMID 41050076, 2025). "Various cancers, including prostate cancer, have taken advantage of the IRE1α-XBP1 pathway to promote pro-survival signals." (PMID 41301006, 2025). "Conversely, a small molecule inhibitor targeting IRE1α was shown to decrease c-MYC levels and inhibit growth of prostate cancer cells and tumors, demonstrating a regulatory feedback loop between XBP1 and c-MYC." (PMID 35349489, 2022). "Genetic inhibition of IRE1α or XBP1 (X-box-binding protein 1, a direct target of IRE1α, activated by mRNA cleavage) inhibits prostate cancer growth in vitro and in vivo." (PMID 31366128, 2019). "Specifically, androgens induce a UPR response in prostate cancer cells, by activating the IRE1α-XBP1 signaling branch, to regulate growth and survival of prostate cancer cells." (PMID 28338058, 2017). "Rosemary extract treatment induced splicing of XBP-1 mRNA in both prostate cancer cell lines compared to untreated controls." (PMID 24598693, 2014). "The IRE1α-XBP1 pathway activates the c-Myc signaling pathway, and androgen receptors also directly upregulate the IRE1α-XBP1 pathway to promote castration-resistant prostate cancer’s survival." (PMID 41301006, 2025). "Furthermore, XBP1 also has a role in IRE1α-mediated upregulation of cyclin A, which in turn enhances cell proliferation in various prostate cancer cell lines." (PMID 35765067, 2022). "Also, AR has been demonstrated to directly bind to the regulatory regions of both IRE1α and XBP-1 and regulate their expression in prostate cancer cells." (PMID 34295814, 2021). "The gene XBP1 of prostate cancer is negatively correlated with the other six genes." (PMID 32846941, 2020). "In prostate cancer cells, Bag5 overexpression inhibits ER stress-induced apoptosis in the UPR by suppressing PERK-eIF2-ATF4 activity while enhancing the IRE1α–XBP1 axis." (PMID 34663798, 2021). "Here, the authors show that one of the canonical UPR pathways, IRE1α-XBP1 regulates c-MYC signaling to promote prostate tumorigenesis, and pharmacological inhibition of IRE1α with MKC8866 inhibits prostate cancer growth and synergizes with clinically used prostate cancer drugs." (PMID 30679434, 2019).